FIGN (fidgetin, microtubule severing factor)
Description:
ATP-dependent microtubule severing protein. Severs microtubules along their length and depolymerizes their ends, primarily the minus-end, that may lead to the suppression of microtubule growth from and attachment to centrosomes. Microtubule severing may promote rapid reorganization of cellular microtubule arrays and the release of microtubules from the centrosome following nucleation. Microtubule release from the mitotic spindle poles may allow depolymerization of the microtubule end proximal to the spindle pole, leading to poleward microtubule flux and poleward motion of chromosome.
Tractability: PROTAC: ubiquitination databases record sites on it.
Gene: Protein-coding gene on chromosome 2 (163,593,396 to 163,736,012, reverse strand). Ensembl gene ENSG00000182263.
Subcellular location: Nucleus matrix; Cytoplasm, cytoskeleton, microtubule organizing center, centrosome
Gene Ontology:
Molecular function: protein binding; ATP hydrolysis activity; microtubule severing ATPase activity; ATP binding
Biological process: microtubule severing
Cellular component: nuclear matrix; centrosome
Genetic constraint (gnomAD): Loss-of-function variants: 8 observed, 52.22 expected, observed/expected ratio (o/e) 0.15, 90% interval 0.089 to 0.28. The upper end of that interval is the gene's LOEUF score, 0.28, which puts it in group 1 of 6, group 1 being the genes least tolerant of losing a copy. Missense variants: 857 observed, 990.07 expected, observed/expected ratio (o/e) 0.87, 90% interval 0.82 to 0.92. Synonymous variants: 406 observed, 378.85 expected, observed/expected ratio (o/e) 1.07, 90% interval 0.99 to 1.16.
Homologues: Orthologues: chimpanzee FIGN (99% identical), rabbit FIGN (99% identical), macaque FIGN (99% identical), pig FIGN (98% identical), guinea pig FIGN (98% identical), mouse Fign (98% identical), rat Fign (97% identical), tropical clawed frog fign (87% identical), dog FIGN (86% identical), zebrafish fign (73% identical), Caenorhabditis elegans figl-1 (21% identical), Drosophila melanogaster Fign (19% identical), and 3 more. Paralogues in human: FIGNL2 (35% identical), FIGNL1 (32% identical), SPAST (21% identical), KATNA1 (18% identical), KATNAL1 (18% identical), KATNAL2 (18% identical), VPS4B (17% identical), VPS4A (16% identical), ATAD1 (13% identical).
Diseases named in the same sentence as FIGN in open-access papers:
FIGN is named in the same sentence as 10 diseases in open-access papers, as found by Europe PMC text mining. Sharing a sentence is not in itself a finding about the gene and the disease. The quoted sentences say what the papers report.
hepatocellular carcinoma (4 papers, 2016 to 2024). A malignant tumor that arises from hepatocytes. "In the recent investigation, it was discovered that hepatocellular carcinoma has downregulated FIGN." (PMID 38421251, 2024). "This research revealed that FIGN expression was tightly related to hepatoma immunity and might be employed as a biomarker to predict patient prognosis and guide medication." (PMID 38421251, 2024). "Further researches on the signaling pathway that FIGN regulates tumorigenesis and development may discover novel therapeutic option to inhibit hepatoma cell proliferation and migration." (PMID 33162817, 2020). "Studies have shown that FIGN is overexpressed in human hepatocellular carcinomas promoting hepatocyte invasion HTRA3 (high temperature requirement A3) is a member of the HtrA family and is a proapoptotic protease shown to promote drug-induced cytotoxicity and proposed to have an antitumour effect." (PMID 32971738, 2020). "Therefore, FIGN may play an important role in tumor progression by regulating hepatoma metastasis." (PMID 33162817, 2020).
colorectal cancer (1 paper, 2020). A primary or metastatic malignant neoplasm that affects the colon or rectum. "Here we demonstrated that CGI hypermethylation of FIGN, HTRA3, BDNF, HCN4 and STAC2 in colorectal cancer is associated with patient progression to metastasis, identifying them as putative future biomarkers for CRC progression." (PMID 32971738, 2020). "In addition, the hypermethylation of FIGN, HTRA3, BDNF, HCN4 and STAC2 could be utilised in primary tumour as biomarkers of colorectal cancer prognosis." (PMID 32971738, 2020).
congenital heart disease (1 paper, 2020). A heart disease that is present at birth. "A genetic variant in FIGN was found to reduce the risk of congenital heart disease in Han Chinese by modulating transmembrane folate transport." (PMID 32574161, 2020).
Down syndrome (1 paper, 2020). "We experimentally validated 2 regions mapping in FIGN and PRR4 genes and showed sex-specific deviations of their methylation patterns in models of decelerated (centenarians) and accelerated (Down syndrome) aging." (PMID 33276343, 2020).
Infertility (1 paper, 2023). "Low AFC, associated with increased risk of infertility, showed an increased expression of a microtubule-severing enzyme (Fidgetin, FIGN), which could represent a marker of developmental quality in oocytes and could be related to oocyte aneuploidy." (PMID 37558907, 2023).
tumor (4 papers, 2020 to 2024). "According to the results of the current study, FIGN has a preliminary role in pro-tumor immunity, including natural killer cell-mediated cytotoxicity, TNF signaling, NF-kappa B signaling, Toll-like receptor signaling, and JAK-STAT signaling." (PMID 38421251, 2024). "The transcriptional expression of FIGN was considerably downregulated in the primary tumor compared to paracarcinoma tissues, according to the results of the non-paired TCGA data analysis (P=0.007)." (PMID 38421251, 2024). "FIGN expression was not substantially different between patients of different ages, tumor stages, T stages, M stages, or N stages, but FIGN expression was significantly different between male and female patients (P<0.05)." (PMID 38421251, 2024). "Notably, FIGN’s mRNA expression was considerably lower in clinical HCC samples than it was in paracarcinoma tissues (P<0.01) When compared to the corresponding normal tissues, FIGN protein expression was reduced in the main tumor (P<0.01)." (PMID 38421251, 2024). "The product of the FIGN gene is involved in essential cellular processes such as mitosis, meiosis, DNA synthesis, and cell migration, and its overexpression may contribute to tumor progression." (PMID 38674360, 2024).
cancer (3 papers, 2020 to 2024). A tumor composed of atypical neoplastic, often pleomorphic cells that invade other tissues. "The results revealed that FIGN expression was decreased in 16 of the 21 cancer types as compared to the normal tissues." (PMID 38421251, 2024). "In contrast, FIGN, HTRA3 and BDNF have been reported in cancer, EMT, invasion/migration process or poor outcome of patients, but our study for the first time links them to methylation status." (PMID 32971738, 2020). "However, the function of FIGN in cancer development and treatment was not intensively studied." (PMID 38421251, 2024).
FIGN also shares sentences with these, for which no sentence is quoted: liver disease (1 paper); Obesity (1); thalassemia (1).